TSC1 (TSC complex subunit 1)
Diseases named in the same sentence as TSC1 in open-access papers (continued):
Sharing a sentence is not in itself a finding about the gene and the disease.
epilepsy (continued). "Mutations in the mTOR-inhibiting (e.g., tuberous sclerosis TSC1, TSC2 and GATOR1 complex) genes are particularly strongly linked to epilepsy." (PMID 36982355, 2023). "In TSC1‐deleted mice, epilepsy occurs within a short time window (8‐12d) of TS and is accompanied by strong activation of the mTORC1 pathway, showing a dose‐dependent response to the mTORC1 inhibitor rapamycin." (PMID 37221133, 2023). "Previous studies similarly reported a higher frequency of epilepsy in general, infantile spasms, and refractory focal epilepsy in patients with TSC2 compared with TSC1 variants." (PMID 37946245, 2023). "A mouse model of TSC with Tsc1 conditional inactivation primarily in glia exhibits progressive epilepsy and premature death." (PMID 35250833, 2022). "The patient demographics presented in this study revealed a high frequency of TSC1 patients and a low prevalence of epilepsy compared to global statistics." (PMID 36232477, 2022). "Statistical analysis revealed that epilepsy occurs with equal prevalence between TSC1 and TSC2 groups (Z = −0.53, df = 1, p = 0.60)." (PMID 35440050, 2022). "Originally, heterozygous Tsc1 or Tsc2 knockout (Tsc1± or Tsc2±) mice showed no seizure episodes, and only one report showed that approximately half of Tsc1± mice showed spontaneously transient characteristics of epilepsy." (PMID 36606143, 2022). "Subependymal nodules (SEN) and cortical tubers were the most frequently appearing lesions, followed by hypomelanotic macules (HM) and epilepsy in TSC1 and TSC2 patients." (PMID 36232477, 2022). "The patient demographics presented in this study had a high frequency of patients with TSC1 and a low prevalence of epilepsy." (PMID 36232477, 2022). "This syndrome is caused by mutations in TSC1 or TSC2, resulting in epilepsy, cognitive disfunction and behavioral abnormalities." (PMID 34820379, 2021). "Astrocyte-specific Tsc1-knockout mice also display epilepsy and some alterations in brain structure." (PMID 33957945, 2021). "Rapamycin and its analogs, that are currently in clinical use to treat epilepsy in TSC patients, curbed epileptiform activity in mouse models harboring TSC1/2, RHEB, MTOR, or PTEN mutations when administered long-term (>7-day)." (PMID 34899181, 2021). "Tuberous sclerosis complex is a multisystem disorder caused by mutations in mechanistic target of rapamycin regulators TSC1 or TSC2, with prominent neurological manifestations including epilepsy, focal cortical dysplasia and neuropsychiatric disorders." (PMID 34632383, 2021). "The first cohort of mice received rapamycin treatment starting on day 4, before the observed increase in CA1 excitability and epilepsy (Tsc1-Cre+-Rap 4)." (PMID 34877936, 2021). "Genetic data were available for 849 individuals with epilepsy; 587 (69.1%) had pathogenic mutations in the TSC2 gene, while 155 (18.3%) had mutations in the TSC1 gene." (PMID 34566842, 2021). "The second cohort received rapamycin on day 8, a time point at which there was significantly increased excitability and epilepsy started to appear (Tsc1-Cre+-Rap 8)." (PMID 34877936, 2021). "The Tsc1-cKO mouse model presents elevated mTORC1 activity due to TSC1 protein reduction, and it exhibits behavioral features of both epilepsy and autism." (PMID 33488359, 2020). "Mutations in TSC1 or TSC2 genes cause tuberous sclerosis complex (TSC), a disorder associated with epilepsy, autism, and intellectual disability." (PMID 32375878, 2020).
epilepsy (continued). "During the follow-up period, a total of 148/174 (85.06%) patients suffered from epilepsy (TSC1:TSC2: NMI = 24:109:15), with 65.54% of those patients manifesting epilepsy within the first year of life." (PMID 32211034, 2020). "Compared with patients with TSC1 variants, NMI patients exhibited more retinal hamartomas (p = 0.035), were less likely to have epilepsy (p = 0.003), and had fewer cortical tubers (p = 0.013) and SENs (p = 0.004) than patients with TSC2 variants." (PMID 32211034, 2020). "Various pre-clinical and clinical studies demonstrated that loss of function mutations of the genes encoding for the natural mTOR inhibitors TSC1 and TSC2 lead to aberrant mTOR signaling with consecutive development of cortical malformations and epilepsy." (PMID 27809914, 2016). "We do not observe other CNS abnormalities, including tuber formation and epilepsy in Tsc1cKO mice where Tsc1 is deleted in the OL lineage." (PMID 27416896, 2016). "Astroglia-specific deletion of Tsc1 or Tsc2 resulted in increased glial proliferation accompanied by epilepsy and premature death." (PMID 26693177, 2015). "We apply the proposed methodology to EEGs from mice where the classes correspond to genotypes of individual mice, of varying inbred strains and with or without the TSC1 knockout associated with epilepsy." (PMID 40894539, 2025). "We describe several genes-including CDKL5, TSC1/2, SCN1a, and TANC2-that have been associated with epilepsy, ASD, or other NDD phenotypes that play a critical role in regulating one or more stages of brain development or function but differ widely in their disease-causing mechanisms." (PMID 41594775, 2025). "TSC1 and TSC2: TSC is a genetic disorder that can cause epilepsy, among other symptoms." (PMID 39867454, 2024). "This study highlighted the potential role of TSC1 in common epilepsy." (PMID 40217423, 2024). "Amongst the most well-known examples of non-ion channel-associated epilepsy genes are TSC1 and TSC2, components of the mammalian target of rapamycin (mTOR) pathway." (PMID 37834053, 2023). "The loss of function of the TSC1/TSC2 complex deregulates these processes with consequent anomalies in development and neuronal activity, which may be responsible for epilepsy and TSC-associated neuropsychiatric disorders (TANDs)." (PMID 36982349, 2023). "Early administration of rapamycin in Tsc1-inactivated mice prevented the development of epilepsy and premature death compared to the untreated mice, while late administration suppressed seizures in mice that had already started having seizures and also prolonged survival." (PMID 35250833, 2022). "Tsc1+/- and Tsc2+/- mutations are known to induce epilepsy in humans, but so far, a spontaneous epilepsy phenotype has not been described in the Tsc2+/- rat or any comparable pre-clinical mouse models." (PMID 33863288, 2021). "Genetic factors, i.e. pathogenic variants in TSC2 rather than TSC1, have been recognized as a significant risk factor for earlier and more severe epilepsy, as well as for a higher rate of cognitive impairment, with due exceptions." (PMID 32216820, 2020). "Compared with TSC1 patients and NMI patients, those with TSC2 variants have a greater chance of developing renal abnormalities, intracranial lesions, and skin diseases, and their age at the onset of epilepsy is younger." (PMID 32211034, 2020). "Compared with individuals with TSC1 pathogenic variants, NMI patients had more retinal hamartomas (p = 0.035), and compared with individuals with TSC2 pathogenic variants, they had less epilepsy (p = 0.003) and fewer subependymal nodules (SENs) (p = 0.004)." (PMID 32211034, 2020). "Interestingly, even post-natal deletion of Tsc1 at 2 weeks of age leads to development of epilepsy in half of the animals, although in a less severe form." (PMID 33041976, 2020).
epilepsy (continued). "Interestingly, inflammatory signaling was recently suggested to be involved in epileptogenesis in a TSC1 mouse model, further highlighting the importance to study inflammatory mechanisms in future efforts to treat TSC-associated epilepsy." (PMID 27655340, 2016). "Indeed, several causal mutations have been identified in patients with epilepsy, the most prominent of these being mutations in PTEN and tuberous sclerosis complexes 1 and 2 (TSC1, TSC2)." (PMID 24672426, 2014). "Indeed, the same aberrations in cortical cytoarchitecture, hippocampal disturbances and spontaneous epilepsy that have been detected in RGC-targeted Tsc2 mutants were observed in RGC-targeted Tsc1 mutant mice." (PMID 23744272, 2013). "In addition, individuals with mutations in TSC1, TSC2, and PTEN, all of which influence cAMP activity and the MTOR pathway all display neurological findings and an increased prevalence of epilepsy." (PMID 24260271, 2013). "TSC is an autosomal dominant genetic syndrome caused by inactivating mutations of TSC1 (hamartin gene) and TSC2 (tuberin gene), characterized by the development of PEComas along with hamartomas, giant cell astrocytomas, and neurologic dysfunction including epilepsy or intellectual disability." (PMID 34442003, 2021). "Conversely, genetic inactivation of Tsc1 and Tsc2 in early embryonic neural progenitors such as NEPs and RGCs, respectively, resulted in very similar neocortical and hippocampal alterations, lamination defects, generation of enlarged cells, cell heterotopias, and epilepsy." (PMID 23744272, 2013). "However, the association between TSC1 variants and common epilepsy has not been determined." (PMID 40217423, 2024). "Different experimental studies have demonstrated that pathogenic mutations in TSC1 or TSC2 can lead to overactivation of mTORC1, resulting in altered neuronal intrinsic excitability (hyperexcitation/hypoexcitation) and/or synaptic transmission disorders, which may be the basis for epilepsy onset." (PMID 38966089, 2024). "Tuberous sclerosis complex (TSC) is an inherited multisystem disorder, comprising both TSC1 and TSC2, and involves a range of symptoms including epilepsy, autism spectrum disorder (ASD), intellectual disability (ID) and slow growing hamartomas in many organs." (PMID 37880800, 2023). "75% of TSC1 patients and 81% of TSC2 patients experienced epilepsy in the form of a range of seizure types." (PMID 35440050, 2022). "Most importantly, single-gene disorders characterized by ASD–epilepsy comorbidity (such as FMR1-, TSC1/2-, and SHANK3-mediated Phelan-McDermid syndromes) are caused by mutations in genes that regulate glutamate receptor-mediated signaling mechanisms." (PMID 36142719, 2022). "Animal models of TSC, created by deletion or knockout of TSC1 or TSC2 in certain cell types, have provided considerable insight into mechanisms by which seizures and epilepsy occur in TSC, as indicated by several experimental observations already discussed." (PMID 28367137, 2017). "Animal models deleting PTEN, TSC1, and TSC2 consistently produce epilepsy phenotypes, demonstrating that increased mTOR signaling can provoke neuronal hyperexcitability." (PMID 24672426, 2014).
epilepsy (continued). "To examine whether the nucleolar enrichment of miR-92b is a general feature of epilepsy, we performed ISH for miR-92b in mice carrying a tuberous sclerosis complex 1 (Tsc1) gene deletion." (PMID 39509000, 2024). "It is believed that heterozygous mutation of Tsc1 or Tsc2 results in the onset of TSC in humans; however, heterozygous knockout of Tsc1 or Tsc2 did not cause hamartoma formation or epilepsy in a mouse model." (PMID 36606143, 2022). "It is therefore of potential importance that reversal of cognitive and social behavior deficits by mTORi was mostly observed in studies conducted in Tsc1+/- and Tsc2+/- mice without an additional epilepsy model." (PMID 33863288, 2021). "To this extent, we used surgically resected brain tissue from patients with drug‐resistant epilepsy due to FCD IIb or TSC and a mouse epilepsy model based on conditional Tsc1 deletion in glial fibrillary acidic protein (GFAP) expressing cells (Tsc1GFAP−/− mice) to investigate these interactions." (PMID 31869431, 2020). "However, there is some controversy as to the specificity of Tsc1 inactivation in Tsc1Cx3Cr1CKO mice, which may not be limited to microglia but likely also affects neurons, and whether more specific postnatal Tsc1 inactivation in microglia causes epilepsy." (PMID 31838997, 2019). "Although this study suggests that TSC1 patients may have a higher remission rate than TSC2 patients, it remains a possibility that a more detailed analysis could prove TSC2 patients have more severe epilepsy." (PMID 36232477, 2022). "Thus, most Tsc1+/− and Tsc2+/− mice are not suitable as models of TSC-associated epilepsy, or brain symptoms caused by a combination of the first hit (normal-sized neurons and glial cells) and the second hit (abnormal giant cells)." (PMID 34206526, 2021). "However, only IS and epilepsy are strongly associated with TSC2 mutations, whereas MR and neurocognitive impairment are linked to different types and location of TSC1 and TSC2 germline mutations, rather than to the specific gene in which the mutation occurred." (PMID 23744272, 2013). "In a study with TSC1 knockout rats, severe epilepsy occured in adult rats without obvious changes in brain structure, suggesting that enhanced mTOR signaling may contribute to epileptogenesis through unknown mechanisms rather than structural changes in brain tissues." (PMID 37221133, 2023). "The investigated Tsc1+/− mouse model exhibits social and cognitive deficits, which are core behavioural symptoms of ASD in humans and other relevant rodent models, without any obvious brain pathology (such as tumors or epilepsy)." (PMID 28775826, 2017).
autism (72 papers, 2010 to 2025). Persistent deficits in social interaction and communication and interaction as well as a markedly restricted repertoire of activity and interest as well as repetitive patterns of behavior. "In contrast, patients with mutations in the TSC1 gene tend to present symptoms associated with anxiety disorders and milder forms of autism." (PMID 40364023, 2025). "We also used a previously reported mouse model of autism caused by Purkinje cell‐specific deletion of the Tsc1 gene from the second postnatal week to study the effect of a moderate perturbation." (PMID 39558452, 2024). "Loss-of-function mutations in the TSC1 gene result in tuberous sclerosis complex, a genetic disorder with high levels of comorbidity for autism." (PMID 39262819, 2024). "Purkinje‐cell specific deletion of tuberous sclerosis complex subunit 1 (Tsc1), an autism‐associated gene for which the protein product negatively regulates the mammalian target of rapamycin, also strengthened cerebellothalamic synapses." (PMID 39558452, 2024). "Using whole‐cell patch‐clamp recordings and optogenetic stimulation, we demonstrated that Purkinje cell ablation and Purkinje cell‐specific deletion of Tsc1 (an autism‐associated gene) in the developing cerebellar cortex strengthen cerebellothalamic synapses." (PMID 39558452, 2024). "An example of an autosomal dominant genetic disorder associated with an increased risk of developing autism, for which there are potentially effective treatment options, is tuberous sclerosis, which is caused by defects of the TSC1 or TSC2 genes." (PMID 36980949, 2023). "Alterations in Rac1 activity were also affected by several autism-risk gene mutations, including fragile X mental retardation 1 (Fmr1), neurexin 1 (Nrx1), neuroligin 4 (Nlg4), and tuberous sclerosis 1 (Tsc1)." (PMID 34671600, 2021). "Tuberous sclerosis complex 1 (Tsc1) suppresses mTOR signaling, and loss of function mutations of Tsc1 cause tumors and a variety of neurological symptoms including intellectual disability, seizures, and autism." (PMID 29163060, 2017). "It was reported recently that conditional deletion of the Tsc1 gene from cerebellar PCs alone was sufficient to cause autism-like behaviors in a mouse model." (PMID 28165338, 2017). "Mice with the 15q11-13 duplication, a model for one form of autism, show defects in cerebellar learning, and mutation of Tsc1 in Purkinje cells alone can recapitulate several autism-like behaviors in mice." (PMID 27077953, 2016). "The first genes implicated in autism were associated with broader syndromes that included autistic symptoms; genes associated with tuberous sclerosis (TSC1 and TSC2) and the tumor suppressor gene PTEN show associations with autistic symptoms." (PMID 24151553, 2013). "It remains essential to examine the functional impact of the missense variants detected in idiopathic ASD to conclude as to whether rare functional variants in TSC1/TSC2 could be a very rare cause of non-syndromic autism." (PMID 23514105, 2013). "Higher burdens of rare, potentially deleterious variants were identified in autism cases for three pathway genes previously implicated in syndromic autism spectrum disorder, TSC1, TSC2, and SHANK3, suggesting that genetic variation in these genes also contributes to risk for non-syndromic autism." (PMID 22558107, 2012). "Additionally, studies using neuronal cultures or transgenic mice have shown that spine density and/or shape were altered after genetic manipulation of proteins implicated in syndromic or non-syndromic autism, including neurexins/neuroligins, Shank2/3, Epac2, Tsc1/2, Ube3A and PTEN." (PMID 28258509, 2017).